EGFR (epidermal growth factor receptor)
Diseases named in the same sentence as EGFR in open-access papers (continued):
Sharing a sentence is not in itself a finding about the gene and the disease.
lung adenocarcinoma (continued). "Ten erlotinib-resistant variants, HCC827-ER1-ER10, were derived from HCC827, an EGFR-activating mutant lung adenocarcinoma cell line." (PMID 31695757, 2019). "Despite these limitations, the present study provides some evidence for the existence of intratumoral heterogeneity of EGFR-activating mutation in lung adenocarcinoma at the level of single cells." (PMID 31014278, 2019). "EGFR tyrosine kinase inhibitors (EGFR-TKIs) have been an effective therapy for lung adenocarcinoma patients with activating mutations; however, therapeutic resistance to EGFR-TKIs inevitably develops." (PMID 31801598, 2019). "This study aimed to compare two methods for the detection of EGFR mutations in circulating tumor DNA (ctDNA) from lung adenocarcinoma (LUAD) patients and to evaluate the clinical significance of EGFR mutations in ctDNA." (PMID 31185703, 2019). "1,760 lung adenocarcinoma patient blood samples were tested for analyzing mutations in EGFR, KRAS, NRAS, PIK3CA, HER2, BRAF and MET in cfDNA." (PMID 31749831, 2019). "Although EGFR tyrosine kinase inhibitors (EGFR-TKIs) are beneficial to lung adenocarcinoma patients with sensitive EGFR mutations, resistance to these inhibitors induces a cancer stem cell (CSC) phenotype." (PMID 31801598, 2019). "In our study, in the largest referral center in the South of Iran, the prevalence of EGFR mutations in lung adenocarcinomas was 28%." (PMID 31531095, 2019). "Among Asian reports, the overall reported EGFR mutation frequency in lung adenocarcinomas were 60% in females and 37% in males." (PMID 31531095, 2019). "In a meta-analysis study in 2015 by Midha in lung adenocarcinomas, the overall EGFR mutation frequency in the Asian Pacific region was 64% in non-smokers against 33% in smokers, and this result was obtained by reviewing 20 studies." (PMID 31531095, 2019). "The frequency of EGFR mutations in lung adenocarcinomas worldwide varies (from 8–13% in European populations to 27–60% Asian populations) according to ethnicity, gender, and tobacco exposure." (PMID 30824880, 2019). "In 10%-35% of lung adenocarcinoma, mutations in the epidermal growth factor receptor (EGFR) gene was found." (PMID 31526459, 2019). "In western countries, rearrangements in the gene (ALK) encoding anaplastic lymphoma receptor tyrosine kinase have been found in only 3–7% of lung adenocarcinomas; in contrast, EGFR mutation is approximately 10–15%, more frequent than ALK rearrangement." (PMID 31455365, 2019). "We showed that a small proportion of patients with lung adenocarcinoma with EGFR mutations exhibited favorable clinical benefits when treated with ICIs, nivolumab and pembrolizumab." (PMID 30790471, 2019). "Lung adenocarcinoma can be classified according to the presence of major driver mutations in EGFR, KRAS, ALK, and BRAF, which confer clinical benefits to the subset of patients harboring them." (PMID 31083279, 2019). "An increased AGR2 expression was also illustrated in 147 cases of surgically resected lung adenocarcinomas that had epidermal growth factor receptor (EGFR) gene mutations." (PMID 31247903, 2019). "Osimertinib is the most recently approved third-generation EGFR-TKI, which can be effective in patients with advanced-stage lung adenocarcinoma harbouring an EGFR gene mutation and an acquired drug-resistant mutation, such as the exon 20 T790 M point mutation." (PMID 30819142, 2019). "This percentage is slightly lower than those of previous studies, which reported approximately half of the patients with lung adenocarcinoma harbouring an EGFR or KRAS mutation." (PMID 31711449, 2019). "Epidermal growth factor receptor (EGFR) gene mutation, especially in exons 18 to 21, is an important predictor of the response rate of lung adenocarcinoma to tyrosine kinase inhibitors." (PMID 31531095, 2019).
lung adenocarcinoma (continued). "Particularly, a recent study reported EGFR mutation enhances glycolysis to maintain cell survival by inhibiting EGFR autophagy-mediated degradation in lung adenocarcinoma cells." (PMID 31444368, 2019). "Screening for these mutations in patients with lung adenocarcinomas can be used to predict which patients will respond to the EGFR TKIs." (PMID 31531095, 2019). "Kirsten rat sarcoma viral oncogene (KRAS) and epidermal growth factor receptor (EGFR) are the most frequent and well-known mutated oncogenes in adenocarcinoma of the lung." (PMID 31783917, 2019). "Since 2010, the evaluation of EGFR mutations in lung adenocarcinoma has been recom- mended as one of the main steps of clinical workups." (PMID 31531095, 2019). "The result of this study provides evidence that gefitinib, erlotinib, and afatinib have similar effectiveness in advance stage EGFR mutation lung adenocarcinoma patients." (PMID 31526459, 2019). "In both studies, we found that ALK-rearranged tumors were more commonly associated with ipsilateral mediastinal or subcarinal lymph node metastasis (N2) compared to ALK wildtype and EGFR mutated lung adenocarcinoma." (PMID 31386689, 2019). "KRAS and epidermal growth factor receptor (EGFR) mutations are the most frequent oncogenic drivers discovered in lung adenocarcinomas." (PMID 31842906, 2019). "This study aimed to detect EGFR gene mutations using next‐generation sequencing (NGS) from different types of body fluids from patients with lung adenocarcinoma." (PMID 31602787, 2019). "Taken together, these results strongly suggest that the EGFR-activating mutation status is heterogeneous in lung adenocarcinoma." (PMID 31014278, 2019). "EGFR-mutated lung adenocarcinoma (LADC) develops through a distinct histogenesis in which micropapillary (mPAP) elements promote tumor progression." (PMID 30973916, 2019). "We predicted the HLA binding epitopes of Del19 mutations of EGFR in Chinese lung adenocarcinoma patients with NetMHC software." (PMID 31722672, 2019). "Two EGFR mutations in exons 19 and 21 account for about 90% of all EGFR mutations reported in lung adenocarcinomas, and are the best predictors of the response and survival benefits of EGFR TKIs." (PMID 31531095, 2019). "Materials and Methods: We included 637 patients with lung adenocarcinomas, who performed the EGFR mutations analysis in the current study." (PMID 31993370, 2019). "Following the identification of KRAS and BRAF mutations, epidermal growth factor receptor (EGFR) mutations were discovered in patients with lung adenocarcinoma and were associated with response to EGFR inhibitors." (PMID 31092229, 2019). "We explored the prognostic impact of TTF-1 expression according to EGFR-sensitizing mutation status in lung adenocarcinoma patients." (PMID 31196060, 2019). "The present study is an extension of our previous work with the goal to explore EGFR mutations associated biomarkers, and visualize EGFR mutation spatial distribution in lung adenocarcinoma (LADC) tissues using ambient AFADESI-MSI." (PMID 31555581, 2019). "They think that the use of upfront WBRT for EGFR-mutated lung adenocarcinoma patients with multiple BM can improve ORR and OS." (PMID 31892337, 2019). "The GGO volume percentage on CT was a predictor of EGFR and exon 21 mutation in lung adenocarcinoma." (PMID 30956990, 2019). "Association between clinical characteristics and the epidermal growth factor receptor mutation status in patients with lung adenocarcinoma." (PMID 31380265, 2019). "The purpose of this study was to explore the prognostic impact of TTF-1 expression based on the EGFR-sensitizing mutation status in lung adenocarcinoma patients." (PMID 31196060, 2019). "Compared with other types of lung adenocarcinoma, lung adenocarcinoma with EGFR mutation shows a good response to treatment with EGFR tyrosine kinase inhibitors (TKIs), such as gefitinib and erlotinib." (PMID 31783917, 2019).
lung adenocarcinoma (continued). "Case 3: A 63-year-old woman was diagnosed with stage IV lung adenocarcinoma with an EGFR mutation (+) (exon 21 L858R) and received erlotinib treatment 150 mg daily." (PMID 31764850, 2019). "There are variable reports from Asian and European countries, as well as North America, about the frequency of the EGFR mutation in lung adenocarcinoma, yet molecular study about this incidence has been published from Iran." (PMID 31531095, 2019). "Lung adenocarcinomas harboring EGFR mutations are a distinct biological subset, as evidenced by their high response rate to TKIs." (PMID 31531095, 2019). "For example, STAT3 mediates the oncogenic effects of EGFR kinase domain mutations in human lung adenocarcinoma." (PMID 31092229, 2019). "Epidermal growth factor receptor (EGFR) gene mutation status is essential to the optimal management of lung adenocarcinoma." (PMID 31602787, 2019). "Although the EGFR S768I mutation is considered to be a very rare mutation, we detected a total of 1.1% patients with lung adenocarcinoma harboring this mutation." (PMID 31749831, 2019). "Our study aimed to evaluate the predicting factors and clinical outcomes associated with concordant results in liquid/tissue biopsy in newly diagnosed lung adenocarcinoma patients with EGFR mutations." (PMID 31652678, 2019). "In conclusion, the present study confirmed the intratumoral heterogeneity of EGFR-activating mutation in lung adenocarcinoma by single-cell analysis." (PMID 31014278, 2019). "Here, we present a study that aimed to detect EGFR gene mutations from different types of body fluids from patients with lung adenocarcinoma." (PMID 31602787, 2019). "In the WJOG8114LTR multicenter, single-arm, prospective phase II study, the clinical significance of monitoring cfDNA was evaluated in 57 EGFR mutated, advanced lung adenocarcinoma patients during treatment with afatinib, an irreversible EGFR inhibitor." (PMID 31861557, 2019). "This study shows for the first time that fluorescent erlotinib can be used as a tracer to distinguish lung adenocarcinoma cells with EGFR mutation from wild-type EGFR, in real time, both in vitro and ex vivo." (PMID 30612556, 2019). "For instance, 17% of lung adenocarcinoma shows sensitive EGFR mutation, with 7% showing ALK mutation and 3% showing MET mutation." (PMID 31766180, 2019). "We compared the performance between deep learning and conventional radiomics on predicting EGFR mutation status of lung adenocarcinoma, which implied the associations of EGFR genotype and radiomic phenotype." (PMID 31074592, 2019). "We retrospectively analyzed 142 patients with EGFR-mutation positive advanced or recurrent lung adenocarcinoma who were administered gefitinib, erlotinib, afatinib, and osimertinib." (PMID 30055587, 2018). "In conclusion, this is a case report of primary resistance to osimertinib in erlotinib-pretreated lung adenocarcinoma with EGFR T790 M mutation." (PMID 30400855, 2018). "In summary, this study showed that several radiomic features were associated with EGFR mutation statuses in lung adenocarcinomas." (PMID 30547844, 2018). "Given that lung adenocarcinoma with EGFR-tyrosine kinase inhibitor (TKI) sensitizing mutation (mEGFR) is common in light and/or non-smokers, Asians, and women, it is expected to have mutational pressures other than cigarette smoking." (PMID 30522449, 2018). "Previous studies established erlotinib was superior to gefitinib in advanced EGFR-mutated patients with leptomeningeal metastases from lung adenocarcinomas that progressed during gefitinib therapy but responded to erlotinib." (PMID 30458751, 2018).
lung adenocarcinoma (continued). "Among the chemotherapeutics available, afatinib has been shown to be effective for those with epidermal growth factor receptor (EGFR) mutation-positive lung adenocarcinoma." (PMID 29805772, 2018). "Activating mutations in the EGFR gene are found in approximately 10–17% of lung adenocarcinoma in Caucasians and in approximately 30–65% of lung adenocarcinoma patients in Asia." (PMID 30409126, 2018). "The prognostic value of epidermal growth factor receptor (EGFR) mutations in the context of serum carcinoembryonic antigen levels remains controversial in T1 lung adenocarcinoma." (PMID 29849818, 2018). "We report two cases of lung adenocarcinoma with EGFR exon 20 mutations and a presentation of diffuse, tiny, innumerable lung and brain nodules resembling miliary metastases." (PMID 30648067, 2018). "For example, lung adenocarcinoma with an EGFR mutation will develop resistance to EGFR inhibitors, either through additional EGFR mutations or through the de novo mutation of MEK." (PMID 30518036, 2018). "In comparison to EGFR-mutated or WT lung adenocarcinomas, ALK-positive tumors had a higher expression of PD-L1 and a higher number of intra-tumoral CD8+ T cells or PD-1+ CD8+ T cells." (PMID 30326973, 2018). "Expression profiling of miRNAs and mRNAs yielded characteristic miRNA/mRNA signatures (19 miRNAs/431 mRNAs) in EGFR-mutated lung adenocarcinoma." (PMID 30404194, 2018). "Taken together, the concordant results in this and previous studies help identify characteristic oncogenic pathways in EGFR-mutated lung adenocarcinoma." (PMID 30404194, 2018). "The epidermal growth factor receptor (EGFR) gene is a key oncogene that is mutated in many tumors including lung adenocarcinomas (LUAD) and glioblastomas (GBM)." (PMID 30518123, 2018). "An integrative analysis of the data was performed to identify the unique miRNA–mRNA regulatory network in EGFR-mutated lung adenocarcinoma." (PMID 30404194, 2018). "Patients with lung adenocarcinoma (n = 156) were enrolled from October 2013 to March 2016, including 56 patients with wild-type EGFR and 100 patients with EGFR mutations." (PMID 28988295, 2018). "The EGFR gene is one of the most frequently mutated and/or amplified gene both in lung adenocarcinomas (LUAD) and in glioblastomas (GBMs)." (PMID 30518123, 2018). "The incidence of lung adenocarcinoma harboring EGFR-TKI-sensitizing mutations is higher in East Asia than in Western countries, and the proportion of non-smokers and women is high, suggesting the presence of mutagenic stressors other than cigarette smoking." (PMID 30522449, 2018). "Our findings, if validated, would inform future research examining the interplay between miRNAs and mRNAs in EGFR-mutated lung adenocarcinoma." (PMID 30404194, 2018). "Further radiogenomic studies with large sample size are needed to nail down those features, which can predict the EGFR mutation in lung adenocarcinomas prospectively." (PMID 30547844, 2018). "We conducted this retrospective study at a single medical center from January 2013 to March 2017 and used PFS to evaluate the effectiveness of gefitinib, erlotinib, and afatinib in patients with advanced lung adenocarcinoma harboring EGFR mutations." (PMID 29849936, 2018). "In fact, there is evidence from transgenic mouse models and cancer cell lines that simultaneous activating mutations in KRAS and EGFR lead to cell death in lung adenocarcinoma." (PMID 29854275, 2018). "In lung adenocarcinoma tissues with an EGFR mutation, the mutation enhances the expression of miR-7 through promoting EGFR phosphorylation." (PMID 30400981, 2018). "Epidermal growth factor receptor (EGFR)-based targeted therapy improves the survival of patients with advanced lung adenocarcinoma harboring EGFR mutations." (PMID 30454543, 2018).
lung adenocarcinoma (continued). "We aimed to investigate the effect of cumulative smoking dose(CSD) on clinical outcomes, including progression-free survival (PFS) and overall survival (OS), in patients with EGFR-mutated lung adenocarcinoma receiving EGFR-tyrosine kinase inhibitors (TKIs)." (PMID 30055587, 2018). "In case of lung adenocarcinoma patients, somatic mutations present in the TK domain of EGFR responds well to TKIs targeting EGFR, but these TKI sensitive mutations in EGFR are very rare in ESCC patients." (PMID 29455652, 2018). "Combination with clinical files, moderate diagnostic performance can be obtained to predict EGFR mutation status of lung adenocarcinoma." (PMID 30547844, 2018). "Subgroup analysis from LUX-LUNG 3 and LUX-LUNG 6 studies demonstrated a significant overall survival benefit for afatinib compared with chemotherapy in stage IIIB/IV lung adenocarcinoma patients with 19del-EGFR mutation." (PMID 29881714, 2018). "In this context, particularly relevant were the studies carried out in lung adenocarcinomas with EGFR mutations and ALK rearrangements." (PMID 30060526, 2018). "Both of these pathways predictably lead to high expression levels of EGFR mRNA, given that EGFR amplification frequently promotes tumor invasion in EGFR-mutated lung adenocarcinoma." (PMID 30404194, 2018). "The levels of OX40 and OX40L were not consistently associated with major clinicopathogical variables, level of T-cell infiltration or with the presence of oncogenic mutations in EGFR/KRAS in lung adenocarcinomas (cohort#3)." (PMID 30400835, 2018). "Identifying the predicting factors for the clinical efficacy of EGFR TKIs in these patients with lung adenocarcinoma harboring uncommon EGFR mutation is urgent." (PMID 30428509, 2018). "Next, we determined the cancer-specific gene mutations in EGFR, a dominant driver in lung adenocarcinomas." (PMID 29721209, 2018). "Our results indicate a potential prognostic role for MAP17 in lung tumours, with particular relevance in lung adenocarcinomas, and highlight the predictive pot0065ntial of this membrane-associated protein for platinum-based therapy and EGFR inhibitor efficacy." (PMID 30119639, 2018). "The percentage of blood S100A9+ MDSC in the EGFR-mutated lung adenocarcinoma patients (17.7 ± 10.6, n = 58) was higher than that of healthy donors (7.5 ± 1.8, n = 7, p = 0.008)." (PMID 29484139, 2018). "Cox regression analyses were used to identify prognostic factors related to the PFS and OS in patients with stage IV lung adenocarcinoma harboring uncommon mutation treated with a first-line EGFR TKI." (PMID 30428509, 2018). "Moderate diagnostic performance was obtained from the combination of radiomic features and clinical presentations to predict EGFR exon 19 and 21 mutations of lung adenocarcinomas." (PMID 30547844, 2018). "Although effective, Gefitinib, Erlotinib, and the other EGFR TKIs are beneficial to only a small population of patients as only about 15% of Caucasian and 50% of Asian lung adenocarcinoma patients harbor EGFR mutations." (PMID 30568916, 2018). "The dataset also consists of figures, tables and Excel files describing the quantitative results of testing these optimized methods in two lung adenocarcinoma cell lines with EGFR mutations." (PMID 29900338, 2018). "In agreement with previous studies of early lung adenocarcinoma, EGFR mutations are major driver mutations in this study." (PMID 29769567, 2018). "Mutations in the epidermal growth factor receptor (EGFR) kinase domain of lung adenocarcinoma have been viewed as the most reproducible predictive factor for susceptibility to first-generation EGFR tyrosine kinase inhibitors (TKIs)." (PMID 29805772, 2018).